CCL5 (C-C motif chemokine ligand 5)
Diseases named in the same sentence as CCL5 in open-access papers (continued):
Sharing a sentence is not in itself a finding about the gene and the disease.
melanoma (continued). "These genes in this set regulated both by EV numbers and tumor CCL5 expression are altered in a variety of solid tumor types, including melanoma, lung, bladder, ovarian, stomach, head and neck, uterine, breast, cervical, colorectal, liver, and prostate cancer as well as high- and low-grade gliomas." (PMID 34298673, 2021). "In particular, the chemokine genes CCL4, CCL5 and CXCL9, which were found to be diminished in HS versus LS cases from TCGA, were previously reported to be part of a gene signature associated with enhanced T cell infiltration in melanoma." (PMID 33806316, 2021). "Survival of patients with melanoma with a high expression of CCL5 was increased." (PMID 32973762, 2020). "We next examined whether reduced homeostatic CCL5 expression has physiological impact on lung metastasis model of B16-F10 melanoma, in which NK cells are known to play a major role in eradicating cancer cells." (PMID 32218434, 2020). "CCL5 is one important chemokine, which has been described to enhance tumor formation and progression, but also to have important immune activating features in melanoma." (PMID 32973762, 2020). "Therefore, these experiments clearly demonstrate that CCL5 was produced intrinsically by the xenografted human melanoma cells." (PMID 32973762, 2020). "CCL5 also promotes the progression of melanoma and pleomorphic glioma." (PMID 32081834, 2020). "Therefore, given that melanoma is highly immunogenic and also immune evasive, inhibiting the CCL5/CCR5 axis with maraviroc was recently proposed as the next step in melanoma immunotherapy." (PMID 32630699, 2020). "In addition, a positive correlation between CCL5 and attraction of NK cells was shown in melanoma patients, and a high expression of CCL5 was correlated with improved patient survival." (PMID 32340261, 2020). "Thus, it has been shown that the expression of CCL4, CCL5, and CXCL10 in melanoma metastases is associated with the recruitment of CD8+ T cells." (PMID 30984181, 2019). "Likewise, recruitment of conventional DCs into melanoma by CCL5 and XCL1, whose production was dependent on NK cells, promoted tumor growth control." (PMID 30899263, 2019). "For instance, an in vivo analysis of anti-tumoral T cell chemotaxis using competitive homing assay showed that key tumor-derived chemotactic factors are CXCR3 ligands, while CCL5, which was also produced by melanoma tumors, is dispensable for direct homing of T cells into the tumor." (PMID 30873179, 2019). "We next assessed whether IL-33 induced the expression of eosinophil-attracting chemokines (CCL11, CCL24, CCL26, and CCL5) in melanoma cells and found significant up-regulation of CCL5 and CCL24." (PMID 31717819, 2019). "Notably, gene expression sequences from melanoma biopsies also revealed a positive correlation between CCL5, CXCL2, CXCL9, and CXCL10 and clinical benefit in a phase II trial of a MAGE-A3 vaccine." (PMID 30899263, 2019). "Interestingly, CCR5 is more highly expressed on tumor infiltrating monocytic MDSC than on peripheral cells and high concentrations of CCL3, CCL4, and CCL5 are found in melanoma lesions, potentially explaining the enrichment of CCR5+ MDSC in tumors." (PMID 30420855, 2018). "The melanoma EV-induced up-regulation of ghrelin, a 28-residue peptide hormone that accelerates the growth of MSCs and has an anti-inflammatory activity, is consistent with the down-regulation of IL-26, IL-17B, caspase-1 and CCL5." (PMID 28129640, 2017). "In melanoma, it has been demonstrated that up regulation of expression of several chemokine genes such as Ccl2, Ccl3, Ccl4, Ccl5, Cxcl9, and Cxcl10 in the tumor microenvironment correlates with the recruitment of activated effector T cells to the tumor increasing antitumor immunity." (PMID 27876058, 2016). "Additionally, the expression of CD44, a receptor for hyaluronic acid and further ligands, e.g. CCL5 was determined at comparable protein levels in glioma cells and melanoma cells." (PMID 26796342, 2016).
melanoma (continued). "Lipopolysaccharides can stimulate normal human melanocytes to produce IL-1β, TNFα, IL-6, IL-8, CCL2, CCl3, and CCL5, and chemotherapy of melanoma-bearing mice results in enhanced expression of CCL5 and the CXCR3 ligands CXCL9, CXCL10, and CXCl11 by tumor cells." (PMID 22745913, 2012). "Indeed, clinical evidence has revealed that elevated levels of tissue or plasma CCL5 are markers of an unfavourable outcome in patients with either melanoma, breast, cervical, prostate, gastric or pancreatic cancer." (PMID 22205974, 2011). "Based on data from The Cancer Genome Atlas (TCGA), melanoma patients were divided into a PRELPhigh and PRELPlow group and associated with clinical parameters, expression of HLA class I APM and IFN-γ signal pathway components, CCL5 as well as the tumor immune infiltration." (PMID 37730606, 2023). "Therefore, DSE expression in melanoma may induce infiltration of CCl5-producing killer T cells and natural killer cells." (PMID 37833287, 2023). "Importantly, M-DM and THP-1 cells show a significantly reduced migration when exposed to CM from melanoma cells overexpressing Bcl-xL treated with CCL5 blocking antibody, and compared to cells exposed to CM from Bcl-xL overexpressing cells treated with control siRNA." (PMID 37488586, 2023). "B cells can differentiate into plasmablast-like cells in melanoma, which express T cells and recruit chemokines such as CCL5, and notably, CCL5 is the key factor involved in the survival of LGG stem cells, thus we speculated that it may also have a similar role in LGG." (PMID 34908101, 2022). "In addition to BECN1 inhibition, targeting other autophagy-related molecules, such as ATG5 or p62/SQSTM1, or inhibiting melanoma autophagy pharmacologically by chloroquine can similarly induce the expression of CCL5 in melanoma cells and consequently enhance the antitumor capacity of NK cells." (PMID 36003368, 2022). "Taken together, the results suggest that our pNK cells with a high expression of CD40L and CCR5 may induce high cytotoxic effects on CD40-high cancers, such as melanoma, breast, and head and neck cancers, or CCL5-high cancers, such as ovarian, metastatic breast, cervical, and gastric cancers." (PMID 34686187, 2021). "Therefore, we cannot draw any conclusions on the role of CCL5 in other non-melanoma tumors." (PMID 32973762, 2020). "Interestingly, a recent study showed that autophagy inhibition could induce CCL5 expression in melanoma cells, resulting in tumor regression facilitated by NK cell migration into the tumor bed." (PMID 32582551, 2020). "Taken together, we assumed that CCL4 and CCL5 may be potent biomarkers and targets for melanoma." (PMID 32508531, 2020). "Furthermore, higher levels of CCL5 in melanoma increased NK cell infiltration, reduced tumor size and could be used as a predictor for patient survival." (PMID 30899263, 2019). "Similarly, the tumour suppressor RUNX3 has been shown to be downregulated in metastatic melanoma lines when compared to primary melanoma or healthy skin, while expression of the chemokine and leucocyte chemoattractant CCL5 in B16 cells strongly suppresses lung metastasis." (PMID 29193607, 2018). "Moreover, macrophages are a major source of CCL2, CCL3, CCL4, CCL5, CXCL9 and CXCL10, which are important chemokines that induce T lymphocyte chemotaxis, and which we find in association with stromal activation in actual melanomas." (PMID 28448494, 2017). "Melanoma-derived fibroblasts secrete factors such as C–C motif chemokine ligand 5 (CCL5), CCL2, and C-X-C motif chemokine ligand 12 (CXCL12), which induce immune checkpoint (ICP) ligand expression in melanoma cells, thereby compromising CD8+ T cell function." (PMID 40399946, 2025). "NF-κB also appears to be responsible for much of the basal expression of CCL2, CCL5, and TNF, possibly a consequence of upregulated NF-κB activity, a common feature of melanoma." (PMID 40507298, 2025).
melanoma (continued). "The data presented in this manuscript focus on CCL5 and CXCL10 as key indicators for evaluating the impact of regulating the expression of ACKR2 in melanoma model." (PMID 40248897, 2025). "Similar results were obtained in a mouse melanoma model, showing that IFN-β stimulates the expression of the ligands CCL5 and CXCR3 and induces tumor infiltration by T-lymphocytes." (PMID 41373826, 2025). "In BRAF- and NRAS-mutant melanoma patients, low ACKR2 expression or high CCL5/CXCL10 levels correlated with improved survival and higher CD8+ T cell markers." (PMID 40248897, 2025). "Based on these findings, we propose that constitutively expressed IκBζ in melanoma recruits HDAC3 and EZH2 to the gene loci of CXCL9, CXCL10, and CCL5, leading to inaccessible promoter regions of these genes." (PMID 40562773, 2025). "Upregulations of Cxcl9, Cxcl10, Cxcl11, Ccl5, Tap1, CD74, Irf1, Icam1, CD40, Fas and PD-L1 were detected after Mi-2β silencing and the anti-PD-1 treatment in BRafV600E/Ptennull melanomas." (PMID 38461299, 2024). "In a melanoma mouse model, the XCL1 and CCL5 produced by NK cells recruited Batf3 DCs to the tumor microenvironment." (PMID 38928238, 2024). "In an in vivo human melanoma model, LCMV treatment up-regulated the chemokine ligand 5 (CCL5, RANTES), supported T cell functionality, promoted NK cell infiltration, and led to immune-mediated melanoma regression." (PMID 38675975, 2024). "Several studies have found a strong correlation between the expression of CCL5 and CXCL10 in tumors and the infiltration of CD8+ T lymphocytes in different types of cancer, such as colorectal cancer, melanoma, and esophageal squamous cell carcinoma." (PMID 38448406, 2024). "In fact, in melanoma models, as the VPS34 kinase inhibitors SB02024 or SAR405 induced a rise in CCL5, CXCL10 and IFN‐γ in the TME along with an increase in the extent of NK and T‐cell infiltration, the inhibition of melanoma was greatly enhanced." (PMID 38652105, 2024). "In a B16 melanoma model, the upregulation of CCL4 and CCL5 recruited Tregs in a CCR5-dependent manner and promoted tumor progression." (PMID 38928238, 2024). "A significant relationship between the infiltration of CD8+ T cells and the expression of CCL5 and CXCL10 has been shown in Ewing sarcoma, melanoma, esophageal cancer, and colorectal cancer." (PMID 39108499, 2024). "Chemokines secretion (CXCR6, CXCL9, CCL5, and CCR5) was also shown to predict response to anti–PD-1–directed therapy in melanoma patients." (PMID 37875556, 2023). "Given that VEGFA, TGFβ1, CCL5 and CXCL2 are released in cell media (CM) as soluble factors, we collected the supernatants from drug resistant A375 and M14 melanoma cells and from their sensitive counterparts." (PMID 36418472, 2023). "The major chemokine/chemokine receptor interactions occurring in melanoma development and progression include the CXCR4/CXCR7/CXCL12, CXCR3/CXCL9,10,11, CXCR1,2/CXCL8, CCR2/CCL2, CCR4/CCL17,22, CCR5/CCL5, CCR7/CCL21 and CCR10/CCL27 axes." (PMID 37170733, 2023). "In the context of cancer, autophagy inhibition is reported to enhance immune cell tumor infiltration by increasing the secretion of pro-inflammatory IFNγ and C–C motif ligand (CCL)-5 (alias RANTES) and CXCL10 chemokine in melanoma, CRC and GBM murine models." (PMID 38071322, 2023). "As was observed for melanoma cells, IFNγ treatment of Ptpn2 knockout CT26 and MC38 cells enhanced the expression of the IFNγ response genes Cxcl1, Ccl5, Stat1, Stat2, Stat3, Irf1, Pd-l1, Tap1, and Casp8, compared with IFNγ-treated control cells." (PMID 36968224, 2023). "In addition, the deletion of another autophagy regulator, Beclin1, inhibited tumor growth in melanoma models by enhancing natural killer (NK) cell infiltration into the tumor region, and the anti-tumor effect is mechanistically regulated by the increased levels of CCL5 chemokine." (PMID 38067169, 2023).
melanoma (continued). "Immune suppressive effects of increased CCL3 have been observed in melanoma and higher levels of CCR5 ligands, CCL3, CCL4 and CCL5, correlated with accumulation of CCR5 + MDSCs in melanoma lesions and tumor progression." (PMID 37964379, 2023). "Recent studies of melanoma model mice and the TCGA melanoma dataset have shown that infiltration of cDC1 in the tumor is induced by XCL1, CCL5, or FMS-like tyrosine kinase 3 ligand (FLT3LG), which are produced by the NK cells infiltrated in the tumor." (PMID 37046775, 2023). "Indeed, our results demonstrated a PRELP-mediated induction of the expression of MHC class I and secretion of CCL5 in melanoma cells, which might contribute (i) to the recruitment of effector T cells into the tumor tissues and (ii) to an increased recognition by CD8+ T cells." (PMID 37730606, 2023). "This is consistent with the TCGA data of global PRELP (log2 5.7 to 13) and PRELPhigh (log2 > 10.6) melanoma with a higher OS (global PRELP; p = 0.00006; log-rank test = 17.72; PRELPhigh; p = 0.002; log-rank test = 9.472) upon high CCL5 expression." (PMID 37730606, 2023). "For melanoma patients treated with OH2 monotherapy, CCL5 levels remained unchanged or decreased in patients with stable disease (SD) and progressive disease (PD), while CCL5 levels elevated in patients having partial response (PR)." (PMID 36438484, 2022). "CXCL9 and CCL5 activated immune responses and enhanced ICB therapy in mouse model of ovary cancer, and the melanoma in CXCR3 knock-out mice exhibited decreased immune infiltration and poor prognosis." (PMID 35692828, 2022). "(CD52, CCL5, and IL32), and was resemble with a group of dysfunctional CD8 T cells recently identified in melanoma, esophageal squamous cell cancer and liver cancer." (PMID 35812401, 2022). "Some of the cytokines produced by human melanoma cells (IL-6, IL-8, CCL5 (RANTES), CXCL1–3 (MGSA-GROa-c), and monocyte chemotactic protein-1 (MCP-1/CCL2) are associated with tumour invasiveness and aggressiveness." (PMID 35334544, 2022). "Together, these data suggest that the IER2-dependent SASP in B16 melanoma cells includes OPN, CXCL15, CCL5, IL-6, and IL-23a." (PMID 34611309, 2021). "In a mouse model of spontaneous melanoma, both DTIC and TMZ have been shown to induce the secretion of chemokines such as CCL5, CXCL9, CXCL10 and CXCL11 by melanoma cells." (PMID 34712615, 2021). "I-BET151 inhibits NF-kB activation in melanoma by targeting BRD2, causing cycle arrest, promoting apoptosis, and inhibiting the production of cytokines (e.g., IL6 and IL-8) and chemokines (e.g., CXCL10 and CCL5), which indicates that I-BET151 may have a therapeutic effect on melanoma." (PMID 34540687, 2021). "In a melanoma mouse model and patients with melanoma, the CCR5+ MDSCs accumulated in tumor tissues were positively correlated with the upregulation of CCL3, CCL4, and CCL5." (PMID 34527668, 2021). "As a similar correlation between CCL5, NK cells and tumor regression can exist in patients, we believe that LCMV-mediated immunotherapy is a new promising therapeutic approach in melanomas." (PMID 32973762, 2020). "Further dissection of cluster 1 induced in IL-32–treated tumors showed significantly increased protein levels of the CCR5-binding chemokines CCL3, CCL4, CCL5, and CXCL2, corroborating the observations in IL-32hi human melanoma." (PMID 32841222, 2020). "An additional study reports a significant expression change of six chemokines (namely, CCL2, CCL3, CCL4, CCL5, CXCL9, and CXCL10) related to the lymphocyte infiltration in the melanoma tissue." (PMID 33302400, 2020). "Furthermore, tumor-infiltrating monocytic myeloid-derived suppressor cells (MO-MDSC) and granulocytic myeloid-derived suppressor cells (PMN-MDSC) from B16-bearing mice could produce higher levels of CCL3, CCL4, CCL5 than that in control mice at melanoma sites, especially MO-MDSCs." (PMID 30800130, 2019).
melanoma (continued). "This plasmablast-like phenotype can be reconciled in human melanomas where plasmablast-like cells also express T cell-recruiting chemokines CCL3, CCL4, CCL5." (PMID 31519915, 2019). "Similar to the analyses of cDC1 and NK cell gene signatures, we observed a positive correlation with survival when we ranked melanoma, HNSC and TNBC patients according to expression of CCL5, XCL1, and XCL2." (PMID 29429633, 2018). "On the other hand, in melanoma, intratumoral injection of IFN-β induces expression of CCL5 and CXCR3 ligands and administration of IFN-β with anti-PD-1 monoclonal antibodies suppressed the tumor growth and prolonged the survival in a murine model." (PMID 29559701, 2018). "In this study, the B16 melanoma cells produced different levels of CXCL1, CXCL10, M-CSF, and CCL5 compared to the B16/BL6 cells." (PMID 30123429, 2018). "A murine melanoma (B16) and a lung carcinoma cell line (LLC) appear to have delayed upregulation of CCL2 and CCL5 transcript levels." (PMID 27852031, 2016). "For instance, expression of CCL3, CCL5 and CXCL2 in melanoma-treated DRG cells increased up to 3.5-, 4- and 3-fold, respectively, compared to control DRG cells (p<0.05, n = 3)." (PMID 27227315, 2016). "For instance, CCL5 and CXCL9 and CXCL10 contributed to the recruitment of CD8 T cells in a mouse model of spontaneous melanoma." (PMID 27096098, 2016). "Several studies indicated that the tumoral expression of CCL5 is tightly related with CD8+ T lymphocytes infiltrating in colorectal carcinoma, melanoma, and sarcoma." (PMID 26317795, 2015). "MCP-1 (or CCL2) and RANTES (or CCL5) increased the infiltration of TAM into primary tumors, including breast and ovarian carcinomas, melanoma, and glioblastoma." (PMID 20490273, 2010). "In addition, we found that IκBζ simultaneously repressed several chemokines such as Cxcl9, Cxcl10, and Ccl5 in D4M-3A, YUMM1.7, and B16-F10 melanoma in vivo." (PMID 40562773, 2025). "In addition, the chemokine CCL5/RANTES, produced by T lymphocytes and macrophages, has a role in the macrophage’s recruitment at the melanoma tumor site, and interleukin-8 and interleukin-1β cytokines are involved in macrophage polarization." (PMID 38542388, 2024). "In melanoma, CCR5/CCL5 recruits Tregs with high TGFβ1 expression." (PMID 38937380, 2024). "We found that IL-6, IL-8, TNF-α and CCL5 were significantly increased in the plasma of metastatic and non-metastatic melanoma patients as compared to HD." (PMID 36860876, 2023). "In addition, PRELP overexpression is accompanied by high CCL5 secretion levels in cell supernatant, an impaired TGF-β signaling as well as a reduced cell proliferation, migration and invasion of melanoma cells." (PMID 37730606, 2023). "Among them, many of these genes have been confirmed to be closely related to melanoma, such as the reduction of MITF level promoting melanoma invasion, tumor regression being abrogated by silencing CCL5 and CST7 being significantly up-regulated in melanoma patients who respond to ICB treatment." (PMID 38008419, 2023). "Inhibition of melanoma autophagy through targeting at ATG5, p62/SQSTM1 and BECN1 activates MAPK8/JNK-JUN/c-Jun signaling pathway in melanoma cells which up-regulates CCL5 cytokine in the TME and thus enhance NK function via activation of NK cell activator NKp46." (PMID 36003368, 2022). "The role of NK cell-derived CCL5 and XCL1 in the recruitment of conventional type 1 dendritic cells (cDC1) leading to the anti-tumor CD8+ T cell response is identified in multiple subcutaneous tumor models including melanoma." (PMID 36733396, 2022). "Indeed, by secreting CCL5 and XCL1, NK cells favored the recruitment of cDC1 in the tumor microenvironment, promoting immune control of melanoma." (PMID 34203391, 2021).